APC (APC regulator of Wnt signaling pathway)
Diseases named in the same sentence as APC in open-access papers (continued):
Sharing a sentence is not in itself a finding about the gene and the disease.
colon carcinoma (continued). "In support, colon cancer cells with APC mutations depend on Wnt ligand signaling for sufficient b-catenin activation." (PMID 30926812, 2019). "Accordingly, bazedoxifene treatment also reduced the growth of patient‐derived colon cancer organoids that harbor the APC driver, and possibly compounding additional mutations." (PMID 30885958, 2019). "We functionally confirmed this observation in IL11‐stimulated human SW480 colon cancer cells that harbor homozygous impairment mutations in the APC gene and therefore show aberrant WNT signaling." (PMID 30885958, 2019). "In colon cancer, the APC gene is frequently mutated generating in a truncated APC product that results in constitutive β-catenin activation." (PMID 31608135, 2019). "A key observation from the tumour models driven by APC loss was that deletion of Bcl9/9l favoured adenoma formation within the proximal SI, whilst colonic tumour growth was suppressed." (PMID 30760720, 2019). "Most colon cancers are associated with mutations in APC or CTNNB1, and ~90% of colon cancers are associated with defects in the canonical Wnt signaling pathway." (PMID 30996256, 2019). "The colonic tumours that formed in VillinCreERApcfl/flBcl9fl/flBcl9lfl/fl mice retained expression of both Bcl9 and Bcl9l, suggesting that BCL9/9l are required for colonic tumour growth following the loss of APC." (PMID 30760720, 2019). "Recurrent RSPO fusions were identified in a subset of colon cancers and were mutually exclusive with APC mutations, suggesting that they are involved in the activation of Wnt signaling." (PMID 30872643, 2019). "To test this possibility, we utilized The Cancer Genome Atlas (TCGA) to identify 104 colon cancer patient samples harboring APC non-sense mutations for which PLK1 expression and clinical meta-data was also available." (PMID 29549256, 2018). "This screening study has used chromatin immunoprecipitation and next-generation sequencing to identify APC-associated genomic regions in colon cancer cell lines." (PMID 30131849, 2018). "Many of these mutant alleles of PDE4B occur in colonic cancers that also carry truncations of the canonical gatekeeper gene APC." (PMID 30188895, 2018). "As a well-defined model system we used specific aneuploid colon cancer cells, because several studies have demonstrated that APC mutations resulting in the expression of N-terminal fragments cause CIN in human colon cancer." (PMID 29549256, 2018). "The results obtained in this APC-driven model indicate a fundamental role of APC loss in colon cancerogenesis and suggest that colon cancer cells can revert to normal intestinal cells given that APC expression is restored in tumor cells." (PMID 29652830, 2018). "APC gene mutations, which are generally early events in the development of colon cancers, can be mined for prophylactic vaccine candidates for the treatment of FAP." (PMID 30256815, 2018). "Inactivation mutations of the adenomatous polyposis coli (APC) tumor suppressor gene are common among more than 50% of colon cancer patients." (PMID 30177619, 2018). "The main binding partner of β-catenin in the colon is TCF4, but colon tumors isolated from APC mutated mice have an increased expression of LEF1 and TCF1." (PMID 29975781, 2018). "It is important to note that in rare cases of colon cancers, the wild-type of the APC, Axin1 or Axin2 gene is mutated." (PMID 29652830, 2018). "The current evidence indicates that mutations at the level of the APC tumor suppressor gene initiate the process of colon tumor formation." (PMID 29652830, 2018). "In colon cancer patients harboring a nonsense mutation within the APC gene which leads to the expression of a truncated APC protein, high PLK1 expression increased patients’s survival significantly." (PMID 29549256, 2018).
colon carcinoma (continued). "The search for inhibitors of Wnt pathway activity in colon cancer cells bearing APC mutations is guided by the concept that only treatments which affect components of the Wnt pathway downstream of APC can be efficient." (PMID 28708837, 2017). "In this study, DFS isolated from A. japonica suppressed TOPFlash activity and suppressed β-catenin nuclear translocation and expression of its target genes in both APC (SW480) or β-catenin (HCT116) mutated colon cancer cells." (PMID 28378765, 2017). "Colitis-associated cancers have distinct molecular characteristics different from sporadic colon cancers, one of which is that Wnt pathway activation caused by APC mutation, which is an early event in sporadic colon cancer, but occurs at later stages in CAC." (PMID 28747693, 2017). "As a TCF/LEF target gene, the Axin2 is highly expressed in colon cancer due to loss of APC tumor suppressor function or β-catenin mutation, and we validated increased Axin2 abundance in colon cancer cell panels." (PMID 28418862, 2017). "APC loss results in nuclear translocation of β-catenin, and strong nuclear β-catenin staining is observed in this colon cancer model." (PMID 29214019, 2017). "This colon cancer cell line presents a mutation in the APC gene and is commonly used as in vitro cell culture prototype for FAP cells." (PMID 29156563, 2017). "Both the initiation and sustained growth of human colon cancers harboring APC mutations rely on the aberrant activation of Wnt target genes." (PMID 28708826, 2017). "Xenograft tumors of (human) colon cancer cell line SW480 (containing homozygous loss‐of‐function mutations in APC and intrinsically activated Wnt signaling) were produced by subcutaneous injection of cells in immunocompromised mice." (PMID 28183841, 2017). "In colon cancers, which are mostly caused by mutations in the APC (adenomatous polyposis coli) gene and/or β-catenin genes, overexpression of Id2 has been observed and attributed to Id2-promoter activation by up-regulated β-catenin." (PMID 28122577, 2017). "Increased β-catenin level in intestinal cells leads to activation of Wnt/β-catenin signaling, followed by occurrence of colon cancer, which was demonstrated by APC-mutation mouse model." (PMID 29190958, 2017). "Mutations in APC have been found in around 80% of all human colon tumors, and these mutations inactivate APC function resulting in Wnt signaling activation by preventing β-catenin phosphorylation and subsequent β-catenin degradation." (PMID 28356914, 2017). "Axin2, a representative downstream target of TCF/LEF transcriptional machinery, is highly abundant in colon cancer cells as well as in adenomas due to loss of APC function." (PMID 28418862, 2017). "Twenty-nine of the 72 colon tumor-associated genes including, e.g., the Wnt-signaling-pathway genes APC, TCF7L2, and FAM123B showed significant specificity for colorectal tumors." (PMID 29296220, 2017). "Specifically, ectopic APC expression decreases CLDN1 expression in Wnt-activated APC-deficient colon cancer cells, and CLDN1 requires its TCF-binding site for transcriptional activation." (PMID 28757546, 2017). "We suspected that a mutation increased the risk of colon cancer, as demonstrated in the APC mutation analysis." (PMID 29237421, 2017). "Activation of Wnt signaling can occur via APC gene mutations and this enables development of colon cancer." (PMID 28298922, 2017). "APC gene mutations have been associated to have a role in colon cancer and since gastric and colon tumors share some common genetic lesions, it is relevant to investigate the role of APC tumor suppressor gene in gastric cancer." (PMID 28576136, 2017).
colon carcinoma (continued). "Human HT29 colon carcinoma cells carrying the APC mutation and Nthy-ori 3–1 immortalized normal epithelial human thyroid cells served as positive and negative controls, respectively." (PMID 27384483, 2016). "A similar repressive activity of hNit1 was detectable in SW480 colon carcinoma cells in which the Wnt pathway is constitutively active due to a mutation in APC." (PMID 27462437, 2016). "Mechanistic investigations revealed that reintroduction of the tumor suppressor adenomatous polyposis coli (APC) into the APC-deficient colon carcinoma cell line HT29 resulted in increased mRNA expression of DHRS9 via the transcription factor CDX2." (PMID 26254099, 2016). "C-terminal truncating mutations of APC, most commonly found in colon cancers, act in a dominant negative fashion to disrupt spindle assembly." (PMID 27097159, 2016). "APC mutations frequently occur at an early stage of colon cancer development and are well documented to increase Wnt signaling by increasing β-catenin stability." (PMID 27097159, 2016). "The β-catenin/TCF4 complex induces the epithelial-to-mesenchymal transition (EMT)-activator ZEB1 to promote tumor invasion in APC-mutated colon cancer." (PMID 27007150, 2016). "Given that the majority of colon cancer patients have APC mutations and active Wnt/β-catenin signaling, these findings establish Hsp110 as a prognostic biomarker and as a potential therapeutic target for the treatment of colon cancer." (PMID 26973652, 2016). "APC mutations were associated with poor prognosis in (5-fluorouracil treated) stage III colon cancers (p = 0.005; HR = 4.1), an effect that was further enhanced by mutations in MAPK pathway (KRAS, NRAS, BRAF) genes." (PMID 27729614, 2016). "The functional contribution of APC mutations to progression of MSS stage III colon cancers is currently not fully understood." (PMID 27729614, 2016). "Miki demonstrated the disruption of the APC gene caused by somatic insertion of a transposon in a colon cancer." (PMID 27649156, 2016). "An example is APC, which shows a strong association with colon cancer, which can be explained by its fine tuning of Wnt-dependent proliferation in rapidly dividing colon crypt cells." (PMID 26856619, 2016). "Inhibition of FZD7 using a dominant negative extracellular domain is able to block the growth of human colon cancer cells in vitro and in xenograft experiments with stably transfected SK-CO-1 cells, which harbour mutations to APC." (PMID 27196929, 2016). "Many of these cancers, in particular colon cancer, gastric cancer and endometrial tumor, are well known for aberrant Wnt signaling activation, evidenced by the prevalence of APC mutations or β-catenin mutations." (PMID 27338477, 2016). "APC functions in the canonical Wnt/Wingless (Wg) signaling pathway in Drosophila and mammals (Drosophila APC is implicated in intestinal stem cell proliferation, and in mammals APC mutants are a direct cause of colon cancer)." (PMID 27436286, 2016). "It is currently unclear how membrane ZNRF3 can block β-catenin signaling in colon cancer cells with β-catenin mutation or APC truncation." (PMID 27338477, 2016). "Knockdown of Hsp110 disrupted the integration of PP2A into the β-catenin degradation complex, resulting in degradation of β-catenin and inhibition of proliferation of colon cancer cell lines that harbor adenomatous polyposis coli (APC) mutation." (PMID 26973652, 2016). "Given that β-catenin and APC mutation is less commonly observed in lung cancer than in other cancer types such as colon cancer, understanding the mechanism by which these Wnt signaling inhibitors regulate the β-catenin destruction complex is crucial." (PMID 26984280, 2016).
colon carcinoma (continued). "Abnormal activation of Wnt/β-catenin signaling, due to loss-of-function mutations in APC or activating mutations in β-catenin has been linked to various human malignancies including melanoma, breast, and colon carcinomas." (PMID 26029888, 2015). "The SW480 colon cancer cells bear a truncating mutation in the APC gene, resulting in stabilization and nuclear accumulation of β-catenin and leading to constitutive activation of β-catenin signaling." (PMID 26029888, 2015). "It is noted that 80% of the cases of sporadic colon cancer, as well as the hereditary forms, are caused by mutations of the APC gene." (PMID 25932044, 2015). "We show that RHBG is expressed in the colon cancer SW480 cells bearing an APC mutation and that its expression is also dependent on TCF4/ β-catenin." (PMID 26029888, 2015). "In human colon cancers, mutations in the Adenomatous polyposis coli (APC) gene are the most common known acquired genetic change for the aberrant activation of the canonical Wnt signaling pathway during tumor development and progression." (PMID 26712794, 2015). "It has been suggested that the loss of adenomatous polyposis coli (APC) function initiates tumorigenesis and that additional genetic and epigenetic events are involved in colon cancer progression." (PMID 26101583, 2015). "A nonsense point mutation in the tumor suppressor gene APC (c.4013C>G, p.S1338X) was previously reported in colon cancer, but was found in one of our cases with rectum cancer." (PMID 25617745, 2015). "It has been suggested that the loss of APC function initiates tumorigenesis and that additional genetic and epigenetic events are involved in colon cancer progression." (PMID 26101583, 2015). "In this context, mutations of adenomatous polyposis coli (APC) occur in more than 60% of colon cancers, which leads to an activation of canonical Wnt/β-catenin signaling." (PMID 26064956, 2015). "Mutations in APC or CTNNB1 are highly frequent in colon cancer and cause aberrant stabilization of CTNNB1, which activates the transcription of Wnt target genes by binding to chromatin via the TCF/LEF transcription factors." (PMID 24651522, 2014). "The majority of cases were reported in colon cancers and involve inactivating mutations of the APC tumor suppressor or mutations that affect axin or β-catenin itself." (PMID 25217618, 2014). "In human colon cancers, mutations in the APC gene are the most commonly known acquired genetic change for the aberrant activation of the canonical WNT signaling pathway during the tumor development and progression." (PMID 25406066, 2014). "Truncating mutations of the APC gene result in the constitutive stabilisation of β-catenin and the initiation of colon cancer, although tumour cells tolerate the expression of wild-type APCL." (PMID 24722208, 2014). "The majority of colon cancer cases result from inactivating, biallelic mutations in APC, which lead to inappropriate accumulation and transcriptional activation of β-catenin." (PMID 25392450, 2014). "Clinicopathologic features of 38 colon cancer patients whose tumor/normal sample pairs were examined for APC mutations." (PMID 25025473, 2014). "We thus further examined 67 tumor/normal sample pairs of rectal cancer, which is very similar to colon cancer in both the cell type origin and genomic alterations showing high incidence of both APC and the CRP-286 SNP mutations." (PMID 25025473, 2014). "Like humans with germline mutations in APC, ApcMin/+ mice have a heterozygous mutation in the Apc gene, predisposing the mice to intestinal and colon tumor development." (PMID 25211188, 2014).
colon carcinoma (continued). "In colon cancer, the Wnt/β-catenin pathway is frequently activated following inactivation of the tumor suppressor APC or mutations in the β-catenin or Axin genes." (PMID 25217618, 2014). "The purpose of this case report is to discuss the significance of a previously reported germline variant of the APC gene, p.R414C, in relation to the development of polyposis and colon cancer in a patient with a clinical diagnosis of attenuated FAP." (PMID 24790607, 2014). "By contrast, a two-fold enrichment of mutant APC were observed in colon tumors with the concurrent CRP-286 SNP mutations (n = 38)." (PMID 25025473, 2014). "Recently, Boutros reported that sustained wnt activity through wnt3a and Evi/Wls/GPR177 can be important for the proliferation in colon cancer cell, independently from APC or β-catenin mutation." (PMID 24564183, 2014). "Mutations in the APC gene have been linked to colon cancer, and scientists have suggested that the mutations inactivate APC in cancer cells to promote unregulated cell growth." (PMID 25406066, 2014). "It was first identified for its role in colon cancer by forming complexes with the tumor suppressor adenomatous polyposis gene (APC) which was followed by characterization of β-catenin mutation in patients with colon cancer 13,14." (PMID 24403228, 2013). "In humans, EB1 was detected as an adenomatous polyposis coli (APC)–interacting protein whose binding domain was affected by APC mutations implicated in colon cancer." (PMID 23844040, 2013). "It is a mechanism that explains how APC mutations induce proliferative abnormalities that drive colon cancer development." (PMID 24224156, 2013). "The tumor suppressor Adenomatous Polyposis coli (APC) gene is mutated or lost in most colon cancers." (PMID 23520519, 2013). "Loss or mutation in the tumor suppressor gene APC (which controls β-catenin degradation) causes adenomatous transformation of intestinal epithelium and it is regarded as the main cause of colon cancer in humans." (PMID 23967107, 2013). "By using our pipeline, we were able to identify a previously unreported homozygous somatic variant in a colon cancer sample predicted to affect APC splicing and six novel somatic mutations with a predicted effect on splicing in leukemic samples." (PMID 24498620, 2013). "SW480 cells harbor a mutated APC gene and mimic the most common mutation found in human sporadic colon cancer." (PMID 23691015, 2013). "PP treatment of colon cancer cells with mutation of adenomatous polyposis coli (APC) and β-catenin inhibited both Wnt signaling and proliferation." (PMID 23061049, 2012). "Two other small molecules, IWR-3 and XAV939, are recently shown to stimulate the degradation of β-catenin by stabilizing axin and thereby inhibiting the proliferation of DLD-1 colon cancer cells, which carry a mutation in APC." (PMID 23071615, 2012). "This has been most firmly established in the gastrointestinal tract, where mutations in the Wnt pathway component, APC and to a lesser degree in β-catenin, activate signalling and are associated with the majority of colon cancers." (PMID 23144924, 2012). "Such a notion gains support by published findings from ours and other laboratories that increased claudin-1 expression in human colon cancer cells bears causal correlation with the APC mutation." (PMID 22719836, 2012). "For example insertions in APC are associated with colon tumors, while EGFR insertions are associated with liver tumors." (PMID 22748055, 2012).